MDM2 (MDM2 proto-oncogene)
Diseases named in the same sentence as MDM2 in open-access papers (continued):
Sharing a sentence is not in itself a finding about the gene and the disease.
cancer (continued). "Four co-opted E3 ligases, such as CRBN and MDM2, were highly expressed in over 15 cancer types." (PMID 37845222, 2023). "Notably, the bioinformatic analysis indicated that AGS activates apoptosis in cancer cells targeting MDM2, which has been shown to play oncogenic roles in human cancers and to represent a valuable target for the development of novel cancer therapeutic agents." (PMID 36672146, 2023). "The MDM2 (human murine double minute-2) is an important target for cancer therapy." (PMID 36677676, 2023). "Overexpression/amplification of MDM2 has been observed in many cancers including GBM." (PMID 37298284, 2023). "Here, we evaluated whether hypoxia could render cancer cells insensitive to two MDM2 inhibitors with different potencies, nutlin-3a and navtemadlin." (PMID 36941277, 2023). "S100A6 and murine double minute 2 (MDM2) are important cancer-related molecules." (PMID 37217945, 2023). "However, the MDM2 gene was suppressed in several types of cancer, including cervical, colorectal, and stomach." (PMID 37049742, 2023).
cancer (continued). "Combined RT and MDM2 inhibition provides synergistic effects in cancer treatment." (PMID 37509518, 2023). "This review aims to summarize the diversified cancer-promoting roles of MDM2." (PMID 37314603, 2023). "Indeed, we found that TSPYL2 accumulation, in male cancer cells, is prevented by the Y-encoded protein SRY, which modulates MDM2 protein levels." (PMID 36918555, 2023). "These two mechanisms are independent of cancer driver mutations but are hindered by high MDM2 p60 expression." (PMID 37845006, 2023). "In this study, we found that H1299 cells are typical Mdm2-overexpressing cancer cell lines." (PMID 38081879, 2023). "MDM2 serves as E3 Ligase regulates cancer cell proliferation in various tumors." (PMID 38041141, 2023). "MDM2-targeting antisense oligonucleotides (ASOs) have been explored as potential cancer therapies." (PMID 37297833, 2023). "Notably, MDM2 has been shown to act as oncogene in human cancers, and different strategies to inhibit MDM2 are under analysis for their treatment." (PMID 36672146, 2023). "Several strategies can be used to target MDM2/MDMX for cancer therapy." (PMID 37509256, 2023). "Together, these results indicate that MDM2 inhibitors retain efficacy in hypoxia, suggesting they could be useful for targeting acutely hypoxic cancer cells." (PMID 36941277, 2023). "In addition to this, the amplification of the MDM2 gene results in an increase in the number of copies of the gene in the cancer cell genome." (PMID 37297833, 2023).
cancer (continued). "Similarly, the natural compound sempervirine inhibits MDM2 E3 ligase activity resulting in apoptosis of cancer cells." (PMID 36923534, 2023). "Amplification of MDM2 has been specifically identified in certain cancer types including LPS." (PMID 36969064, 2023). "Consequently, MDM2 has been the subject of extensiveresearch aimed at developing novel cancer therapies." (PMID 37779953, 2023). "MDM2 amplification or overexpression is observed in many cancers." (PMID 37296881, 2023). "The phosphorylation or methylation of MDM2 in the promoter region may be responsible for the different roles in several types of human cancer." (PMID 37049742, 2023). "MDM2-mediated metabolic reprogramming plays a fundamental role in the progression of cancer." (PMID 37314603, 2023). "Although the development of MDM4 inhibitors lagged behind that of MDM2 inhibitors, it has been increasingly promoted in recent years, in part by research showing that the persistent expression of MDM4 in cancer cells counteracted the cytotoxic effects of MDM2 inhibition." (PMID 37686602, 2023). "The combination of USP7 inhibition with anti-MDM2 therapy and PD-1 blockade may appear highly effective in enhancing cancer immunotherapy." (PMID 36428632, 2022). "MDM2 is an oncogene related to several human cancers and canine neoplasms." (PMID 35898539, 2022).
cancer (continued). "Furthermore, for nearly 10–15% of malignant gliomas, MDM2 genes were listed as the second most frequently augmented gene in these malignant tumors." (PMID 36654821, 2022). "Of these, MDM2 is a known oncogene amplified across multiple cancer types." (PMID 36439412, 2022). "The expression of both 53 and Mdm2 was localized mainly in the nucleus of the cancer cells." (PMID 35369583, 2022). "In addition, in this study, the Mdm2 expression was significantly higher around the cancer island of the cattle SCC, especially in the poorly differentiated samples." (PMID 35369583, 2022). "Interestingly, increased longevity was observed in females with SNP309T>G MDM2 if they didn’t suffer from cancer diagnoses." (PMID 35155432, 2022). "This study investigated the anti-cancer effects of Hinokiflavone through targeting MDM2." (PMID 35625571, 2022). "Thus, inhibition of MDM2 activity has been pursued as an attractive direction for the development of anti-cancer therapeutics." (PMID 35625571, 2022). "Thus, Nutlin-3 in combination therapy sensitizes many cancer cell types, but shows less effect in those with poor MDM2 expression." (PMID 35563397, 2022). "Additionally, its optimized α-helical stability resulted in improvement in cell permeability, in vivo stability, favorable PK properties, and, consequently, potent cellular and in vivo antitumor activity in cancers that overexpress MDM2 or MDMX." (PMID 36678521, 2022). "Another small molecule, triptolide inhibits mRNA expression of MDM2 in cancer cells." (PMID 36043494, 2022).
cancer (continued). "MDM2 is also in the same chromosomal amplicon as CCT2 that is highly expressed in cancer cells." (PMID 35602608, 2022). "The activity of HAUSP on pRb was subject to MDM2 in a context-specific fashion, where HAUSP deubiquitinated and stabilized pRb with low level of MDM2 in normal cells while high level of MDM2 hampered HAUSP activity on pRb leading to pRb degradation in cancer cells." (PMID 35650644, 2022). "As such, MDM2 has been suggested as a promising target for cancer treatment." (PMID 35475453, 2022). "Therefore, the -309 T/GMdm2 SNP and the overexpression of Mdm2 increase cancer riskand accelerate tumorigenesis." (PMID 35293553, 2022). "Indeed, if administered at higher doses, nutlin, first rationally-designed MDM2 inhibitor, was shown to reactivate TAp73 and induce cancer cells apoptosis." (PMID 35806218, 2022). "Moreover, amplification of the MDM2 gene has been reported in other malignant tumors, justifying the integration of molecular data with histological data." (PMID 36164527, 2022). "Based on TCGA database, Pearson correlation analysis revealed MDM2, an E3 ubiquitin ligase involved in ubiquitin-mediated proteolysis with critical functions in cancer, was positively correlated with CERS6-AS1 and chosen among the candidate genes for further study." (PMID 35927226, 2022).